IL2 (interleukin 2)
Diseases named in the same sentence as IL2 in open-access papers (continued):
Sharing a sentence is not in itself a finding about the gene and the disease.
schizophrenia (continued). "We suggest the negative direction of association mirrors consistently the frequent reports of increased IL-2 activity in disorders such as schizophrenia and Parkinsonism with a very different clinical profile." (PMID 20534153, 2010). "Higher BMI in chronic schizophrenia is associated with reduced IL-2 levels, attenuated negative symptoms, and adverse lipid profiles." (PMID 40791199, 2025). "Another possible reason was that IL-2 might interact with certain inflammatory factors in the symptomatic mechanism of schizophrenia including a pathological mechanism of inflammatory damage from IL-2 compensation." (PMID 38627438, 2024). "We also found an increase in serum IL-2 concentration in schizophrenia." (PMID 37239308, 2023). "In schizophrenia, neuroinflammation denotes the initiation of the brain’s immune response, which is principally driven by microglial cells and the discharge of inflammatory cytokines like IL-2, IL-4, IL-13 IFN-γ, and TNF-α." (PMID 38256307, 2023). "It is known that IL-2 may play a role in the pathogenesis of schizophrenia in the context of the T-reg hypothesis." (PMID 37239308, 2023). "Interestingly, in animal studies, the offspring of mothers injected with IL-2 developed schizophrenia-like symptoms." (PMID 36138890, 2022). "In addition to animal experiments, some human experiments have proved that IL-2 affects the therapeutic effect of schizophrenia or that the IL-2 level changes after antipsychotics treatment." (PMID 36138890, 2022). "The role of IL-2 in schizophrenia was discussed in this review." (PMID 36138890, 2022). "Taken together, our findings suggest that IL-2 or sIL-2R may be potential biomarkers for schizophrenia." (PMID 36138890, 2022). "The objectives of this review are to explore the possible impact of IL-2 on the prevalence and progression of schizophrenia, as well as the potential of IL-2 to be used as a marker of schizophrenia in order to provide novel insights for the treatment of schizophrenia." (PMID 36138890, 2022). "The effect of IL-2 has been widely studied in different aspects of schizophrenia." (PMID 36138890, 2022). "As early as the last century, studies had suggested a correlation between IL-2 and schizophrenia." (PMID 36138890, 2022). "In addition, we focused on the changes of IL-2 in the onset, progression and treatment of schizophrenia and the possible mechanisms by which IL-2 affects schizophrenia." (PMID 36138890, 2022). "However, further prospective validation is needed to define the molecular mechanisms through which IL-2 influences schizophrenia initiation and development." (PMID 36138890, 2022). "Taken together, these studies suggest a potential genetic link between IL-2 and schizophrenia." (PMID 36138890, 2022). "Higher CSF levels of IL-2 in neuroleptic-free schizophrenia patients could result in elevated DA neurotransmission and may contribute to psychotic symptoms." (PMID 33362607, 2020). "We also found that IL-2 was increased in schizophrenia, again consistent with previous reports." (PMID 29803226, 2018). "Our finding of lower levels of IL-2 mRNA expression in people with schizophrenia may also suggest that in schizophrenia more T cells escape this important regulatory step and thus, people with schizophrenia may be expected to have more self-reactive T cells." (PMID 28923068, 2017). "We hypothesised that pro-inflammatory cytokines may be elevated and the anti-inflammatory IL-2 may be reduced in schizophrenia compared to healthy controls." (PMID 28923068, 2017). "Lower levels or lower function of IL-2 may be at least a partial explanation of why more brain autoantibodies can be found in blood and cerebrospinal fluid of people with schizophrenia." (PMID 28923068, 2017). "TD patients have different serum IL2 levels from non-TD patients, and the concentration of IL2 is associated with the negative symptoms of schizophrenia." (PMID 23951054, 2013).
schizophrenia (continued). "Notably, we were unable to find a significant association between the remaining polymorphisms (IL2 −330T>G, IL6 −174G>C, IFNG +874T>A, TGFB1 +913G>C) and schizophrenia in our study." (PMID 24065520, 2013). "For example, several interleukin genes (IL2, IL3, IL4) have been implicated for schizophrenia." (PMID 20613869, 2010). "IL-2 seems to be particularly associated with negative and cognitive symptoms of schizophrenia." (PMID 36138890, 2022). "Moreover, the levels of IL-2 in patients with schizophrenia often differ from healthy controls." (PMID 36138890, 2022). "Therefore, the IL-2/IL-2R pathway could be a mechanistic link between schizophrenia and autoimmune conditions, and a potential therapeutic target for schizophrenia." (PMID 34280516, 2021). "If true, IL-2 may have a key role in the pathophysiology of schizophrenia." (PMID 33746786, 2021). "While the underlying cause of the cytokine dysregulation we have found here is not known, decreased IL-2, increased IL-6, IL-8 and TNFα have all been associated with Toxoplasma gondii infections, of which the seroprevelance is increased in schizophrenia." (PMID 28923068, 2017). "Thus, it may be that people with schizophrenia have a blunted ability to dampen or attenuate unwanted inflammation via producing less IL-2." (PMID 28923068, 2017). "There are no data on the impact of combinations of antipsychotics in TRS patients on other cytokines, e.g., IL-2, IL-4, IL-5, IL-10, IL-12, IL-17, IL-23 and TGF-β1, although their involvement in schizophrenia pathophysiology has been demonstrated." (PMID 39595201, 2024). "IL-1β, IL-2, IL-4, IL-6, BAFF, IFN-α, GM-CSF, NRG1-β1, and GDNF increased but TNF-α and NGF-β decreased in schizophrenia compared to healthy individuals." (PMID 37239308, 2023). "The signs of activation of Th2 immune response in schizophrenia include the increase of the IL-4 and IL-10 levels in blood serum, decrease of Th1/Th2 cytokine level ratio (IFN-γ/IL-4, IFN-γ/IL-10, IL-2/IL-4, TNF-α/IL-4)." (PMID 39944368, 2023). "Cytokine levels including IL-2, IL-4, IL-6, IL-10, TNF-α, and IFN-γ were tested, and we found significantly higher levels of IL-6 in patients with schizophrenia (P < 0.01)." (PMID 38066312, 2023). "Among these, the study of Smith and Maes proposed that in schizophrenia, chronically activated macrophages and T lymphocytes produce cytokines, such as TNF-α, IL-1, IL-2, IFN-α, and IFN-γ, that have a key role in this disorder's development." (PMID 33746786, 2021). "The data shown in depicted that cytokines including IL-2, IL-6, and TNF-α play a considerable role in the development of schizophrenia." (PMID 33995058, 2021). "We also investigated markers of inflammatory response (C-reactive protein, IL-2, IL-6, IL-10), the activity of leukocytic elastase (LE) and α1-proteinase inhibitor (a1-PI), antibodies to S100B and myelin basic protein (MBP) in schizophrenia." (PMID 34025476, 2021). "Data from 62 studies, analyzed IFN-γ, IL-4, IL-2, soluble IL-2 receptor (sIL-2R), IL-1β, IL-1 receptor antagonist (IL-1RA), TNF-α, IL-6, soluble IL-6 receptor (sIL-6R), and IL-10 in schizophrenia." (PMID 33746786, 2021). "Plasma levels of interleukin (IL)-1β, IL-2, IL-6, and interferon (IFN)-γ were elevated in schizophrenia patients compared to those in controls." (PMID 29803226, 2018). "A meta-analysis of cytokine changes in the peripheral blood has identified IL-2, IFN-gamma, TNF-alpha and soluble IL-2 receptor as trait markers of schizophrenia because their levels were elevated during acute exacerbations and reduced in remission." (PMID 25563714, 2015). "Strong correlations with immune system pathways were found which involve the IL-2 and TREM-1/DAP12 pathway which are responsible for the etiology mechanism for schizophrenia in PID." (PMID 24564241, 2013). "A real-world study showed that the IL-2 level is a key factor in predicting negative symptoms and cognitive impairment in outpatients with schizophrenia." (PMID 36138890, 2022).
schizophrenia (continued). "When comparing 29 outpatients with chronic medication who received schizophrenia treatment with 26 healthy controls, IL-2 level was found to have negative correlation with the degree of negative symptoms and language disorder." (PMID 36138890, 2022). "IL-2 was not significantly altered after treatment in schizophrenia patients (g: −0.18; CI −1.00 to 0.65; p = 0.676; I2 = 91%) nor after treatment in MDD patients (g: −0.98; CI −3.82 to 1.86; p = 0.50; I2 = 97%)." (PMID 33653423, 2021). "Residual schizophrenia, and its most known manifestation (cognitive impairment), is characterized by a typical biochemical decrease in BDNF and TNF-α, and at the same time an increase in IL-2, IL-6, and IL-8." (PMID 34434228, 2021). "Also we investigated associations between some immunological patterns and markers of inflammatory response (CRP, IL-2, IL-6, IL-10, the activity of LE and a1-PI, antibodies to S100B and MBP) with clinical symptoms in schizophrenia." (PMID 34025476, 2021). "Our results do not support the association of polymorphisms in IL2, IL6 and IFNG genes with schizophrenia." (PMID 24065520, 2013). "For example, the over-expressing schizophrenia candidate genes, SIRPB1, SYK and LCK, are responsible for signal transduction in cytokine production; immune responses involving IL-2 and TREM-1/DAP12 pathways are relevant for the etiology mechanism of schizophrenia." (PMID 24564241, 2013). "Here, we analyzed changes in serum concentrations of cytokines (IL-1β, IL-2, IL-4, IL-6, IL-10, IL-21, APRIL, BAFF, PBEF/Visfatin, IFN-α, and TNF-α) and growth/neurotrophic factors (GM-CSF, NRG1-β1, NGF-β, and GDNF) in patients with schizophrenia in an exacerbation phase." (PMID 37239308, 2023). "However, the results of these studies vary largely, with some studies showing an increase in the level of IL-2 in in patients with schizophrenia, while some found a decrease or no change." (PMID 36138890, 2022). "Another responsible pathway involves the IL-2 pathway which Interleukin-2 binds to the IL-2 receptor to activate LCK and SYK, which helps explain that the over-expression genes: SIRPB1, LCK and SYK might be responsible for one of the possible disease mechanisms for schizophrenia." (PMID 24564241, 2013). "However, schizophrenia patients are unable to produce sufficient amounts of BDNF to mitigate the inflammatory damage induced by IL-259, and a negative correlation between BDNF and IL-2 levels was observed in our study." (PMID 40133606, 2025).
multiple sclerosis (54 papers, 2006 to 2026). A progressive autoimmune disorder affecting the central nervous system resulting in demyelination. "Interleukin-2 (IL-2) has been implicated in neurological disorders including multiple sclerosis and Alzheimer’s disease." (PMID 25961067, 2015). "In the CNS, the expression of IFNα, IL-2, and IL-12 is linked to experimental autoimmune encephalitis (EAE), multiple sclerosis (MS), Alzheimer’s disease (AD), and Parkinson’s disease (PD) (59, 84, 87, 117, 118, 120, –, 122) through amplified Th1 responses." (PMID 39087762, 2024). "LIPS has even been used to rule out the presence of some autoantibodies in certain diseases including against KIR4.1 in multiple sclerosis, IL-2 in T1D, and ezrin in pancreatic ductal cancer." (PMID 36979515, 2023). "For example, animal models of multiple sclerosis (MS) show that statins skew immune responses towards an anti-inflammatory T-helper cell 2 response, inhibiting pro-inflammatory cytokines IL-2, IL-12 and IFN-γ70." (PMID 35118196, 2020). "It revealed that sildenafil can decrease the levels of TNF-α, interferon (IFN)-γ, IL-2 and IL-1β in animal model of multiple sclerosis." (PMID 28210757, 2017). "As such, the combination of IL-2 and a calcineurin inhibitor (Cyclosporine A; CsA) expands Tregs while inhibiting Tconv proliferation and protects against a mouse model of multiple sclerosis." (PMID 24658577, 2014). "To evaluate the role of cellular infiltrates in CNS demyelination in immunocompetent mice, we have used a model of multiple sclerosis (MS) in which different strains of mice are infected with a recombinant HSV-1 expressing IL-2." (PMID 21364747, 2011). "However, in experimental models of multiple sclerosis, fenofibrate reduced expression of IL-2, IL-6 and key Toll-like receptor signaling components (including CD14), thereby decreasing microglial activation and pro-inflammatory mediator secretion." (PMID 41009625, 2025). "In the context of multiple sclerosis, IL-2 contributes to both pro-inflammatory responses through the activation and expansion of autoreactive T cells and anti-inflammatory responses by promoting the development and function of Treg, which are key to maintaining immune tolerance." (PMID 39000506, 2024). "The IL-2:IL-6 ratio, IL-2, and chitinase 3-like 2 (all in cerebrospinal fluid) might be of value as prognostic biomarkers in early phases of multiple sclerosis." (PMID 35759479, 2022). "•The IL-2 – IL-2R pathway is involved in the pathogenesis of multiple sclerosis." (PMID 35005590, 2021). "Interleukin 2 (IL-2) is considered a key player in exacerbating multiple sclerosis (MS)." (PMID 32244639, 2020). "IL-2/anti-IL-2 antibody immune complexes, as well as complexes involving other cytokines, have been considered for treatment in immuno-oncology, auto-immune disorders, viral and bacterial infections, and multiple sclerosis." (PMID 26870966, 2016). "Many of these cytokines such as interleukin 6, IL-2 T cell growth factor, tumor necrosis factor alpha (TNF-α) are also involved in the regulation of signaling pathways in the development of multiple sclerosis." (PMID 36232592, 2022). "In multiple sclerosis and EAE, there is inappropriate T cell activation as well as abnormal IL-2 and TH17 skewing conditions within the cerebrospinal fluid (CSF) and serum." (PMID 25153088, 2014). "Previous studies have shown that cytokines, including IL2 and the TH17 skewing cytokines (IL23, IL6, TGFβ), are abnormally present in the CSF of some patients with multiple sclerosis as well as in mice immunized for EAE." (PMID 25153088, 2014). "Furthermore, we confirmed that this synergistic effect is conserved in human T cells from patients with multiple sclerosis (MS) upon CTLA-4 Ig and IL-2 cotreatment." (PMID 42086904, 2026).
multiple sclerosis (continued). "Associations were found between change scores in (i) Six Spot Step Test and Interleukin (IL)-2, IL-8, and IL-17 levels; (ii) timed 25-foot walk and interferon-γ, IL-2, IL-8, TNF-α, and neurofilament light levels, and (iii) 12-Item Multiple Sclerosis Walking Scale and IL-17 levels." (PMID 38338871, 2024). "Mice with brain-specific IL-2 delivery were protected in traumatic brain injury, stroke and multiple sclerosis models, without impacting the peripheral immune system." (PMID 35618831, 2022). "It is observed that drugs used to treat multiple sclerosis such as glatiramer acetate, dimethyl fumarate, and monomethyl fumarate upregulate the expression of chemokines receptor 10 (CCR10) on the surface of human IL-2-activated NK cells." (PMID 27807435, 2016). "IL-2, IFN-γ, and TNF-α levels are increased in HTLV-1 infection and contribute to neurological damage in HAM/TSP patients as well as in other neuroinflammatory conditions with clinical similarities to HAM/TSP such as Multiple Sclerosis." (PMID 23409198, 2013). "Notably, NK17/NK1 cells are abundant in the cerebrospinal fluid (CSF) of patients with multiple sclerosis (MS) without activation, and are generated from the peripheral blood of these patients after activation with IL-2." (PMID 22039549, 2011). "Additionally, MTO is approved to treat different forms of multiple sclerosis as it presents immunosuppressive activity such as the inhibition of B-cell, T-cell and macrophage proliferation and a decrease in the secretion of tumor necrosis factor alpha (TNF-α) and interleukin-2 (IL-2)." (PMID 35886997, 2022).
sarcoidosis (54 papers, 2008 to 2025). Sarcoidosis is a multisystemic disorder of unknown cause characterized by the formation of immune granulomas in involved organs. "Dysregulation of this pathway, particularly through cytokines like IFN-γ, IL-2, and IL-23, is implicated in the pathogenesis of sarcoidosis, with evidence showing increased JAK/STAT activity in affected tissues." (PMID 40351964, 2025). "A hallmark of active sarcoidosis is the predominant expression of interferon-gamma in the affected organs, accompanied by the involvement of active cytokines, such as IL-2, IL-12, and tumor necrosis factor-alpha." (PMID 39598118, 2024). "Reduction of active CD4+ T cells in lung tissue and normalization of IL-2 levels are associated with spontaneous clinical resolution of sarcoidosis." (PMID 37062818, 2023). "Recent evaluation of the diagnostic value of different serum biomarkers in sarcoidosis has revealed the best performance of serum angiotensin converting enzyme (sACE), soluble IL-2 (sIL-2R) receptor, and chitotriosidase (CTO)." (PMID 37959363, 2023). "Antineoplastic therapies—including interferons, cisplatin, and interleukin 2—have previously been established to be associated with sarcoidosis." (PMID 26083934, 2015). "There are theories regarding a link between sarcoidosis and cytokines, including Th1, IL-2, IL-6, IL-8, IL-12, IL-18, IL-27, interferon gamma, and tumor necrosis factor." (PMID 40259952, 2025). "The levels of IL-1β were slightly lower in sarcoidosis patients than in HP (p = 0.04) and amiodarone lung (p = 0.03) patients, and the levels of IL-2 were higher in sarcoidosis patients than in amiodarone lung (p = 0.006) patients." (PMID 40725075, 2025). "While our study focused on causal inference, our findings also support the involvement of the interleukin-2 pathway and serum amyloid A in sarcoidosis." (PMID 40075078, 2025). "In fact, Drake’s group, in 2013, showed that sarcoidosis results in decreased production of IL-2 and INFγ, resulting in reduced CD4+ T lymphocyte activity." (PMID 37761266, 2023). "High IL-2 is released by activated T cells during active disease and low IL-2 in chronic sarcoidosis; therefore, IL-2 is an early marker in active sarcoidosis." (PMID 37367586, 2023). "Many cytokines implicated in sarcoidosis including IFN-γ and IL-2 (Type 1), IL-23 (Type 3), and IL-4 and IL-13 (Type 2) signal via the JAK – signal transducer and activator of transcription (STAT) pathway." (PMID 35668129, 2022). "With an already diagnosed and azathioprine-treated sarcoidosis, patient 6 developed a severe disease progression in spite of multimodal medical therapy with mirtazapine, mefloquine, cidofovir, intravenous IL2, and JC virus vaccination." (PMID 34377151, 2021). "Cytokine production in sarcoidosis was initially featured by an increase in Th1 cytokines (IL-2, IL-6, IL-12, IL-18, TNFα, IFNγ), which is potentially responsible for the so-called classical (M1) macrophage activation." (PMID 32751786, 2020). "In one study, peripheral CD4+ T-cells from sarcoidosis patients were found to have spontaneous secretion of IL-2 and IFN-γ that exceeded that of healthy controls." (PMID 33036432, 2020). "CD4+ T lymphocytes which are the one of the primary cells involved in immunopathogenesis of sarcoidosis releases interleukin-2 (IL-2) and interferon-γ (IFN-γ)." (PMID 23533794, 2013). "Interleukin-2 and interleukin-12 mRNA expression of PBMCs after stimulation with P. acnes is also higher in patients with sarcoidosis than in control subjects." (PMID 23844371, 2013). "Granulomas in early sarcoidosis express a strong TH-1 phenotype with production of interleukin-2 and IFNγ, which results in a positive feedback loop to recruit additional TH-1 cells and IFNγ production." (PMID 22937766, 2012). "Levels of IL-2 and IL-8 were elevated in both diseases compared to healthy volunteers but these increases only reached statistical significance in sarcoidosis." (PMID 22815689, 2012).